USP9X (ubiquitin specific peptidase 9 X-linked)
Diseases named in the same sentence as USP9X in open-access papers (continued):
Sharing a sentence is not in itself a finding about the gene and the disease.
multiple myeloma (17 papers, 2013 to 2023). "Increased USP9X mRNA in tumors has been significantly associated with poor prognosis for patients with multiple myeloma, and patients highly expressing USP9X mRNA have a 5.5-fold greater risk of death." (PMID 27783990, 2016). "The deubiquitinase USP9-X is overexpressed in lymphomas and multiple myeloma and stabilizes MCL-1 by removing K48-linked polyUb chains." (PMID 25340740, 2014). "USP9X has been shown to regulate multiple cellular functions, and increased expression of USP9X in tumors is significantly associated with poor prognosis for patients with multiple myeloma." (PMID 24890815, 2014). "Such knowledge may be of prognostic value, as an increase in USP9X expression in multiple myeloma patients was associated with poor prognostic outcomes, and increased USP9X expression in oesophageal squamous cell carcinoma was correlated with poor survival after radical surgery." (PMID 25672900, 2015). "USP24, which is closely related to USP9X, also plays a critical role in the survival of myeloma B cells by regulating MCL1 protein levels." (PMID 32354135, 2020). "We have recently identified and developed a compound with improved specificity towards USP9X and antitumor activity in mouse models of myeloma, lymphoma and melanoma (unpublished data, Potu H and Donato NJ, 2014)." (PMID 25606592, 2014). "Increased USP9X expression is reported in human follicular lymphoma and correlates with poor prognosis in multiple myeloma." (PMID 25606592, 2014). "Overexpression of USP9X is reported in follicular lymphoma, diffuse large B-cell lymphoma and multiple myeloma." (PMID 24152793, 2013). "In the same study, increased USP9X in multiple myeloma patients correlates with poor survival and the authors conclude that USP9X stabilizes MCL1, one member of pro-survival BCL2 family, and promotes tumor cell survival." (PMID 24152793, 2013). "However, upregulation of USP24 in response to USP9X knockdown, promoting myeloma cell survival, demonstrated the need for dual USP9X/USP24 inhibitors, prompting the development of EOAI3402143 (aka G9) by improving the properties of WP1130." (PMID 34203106, 2021). "Furthermore, multiple myeloma patients with high level of USP9X had a poorer overall survival rate and prognosis compared to patient with lower USP9X levels." (PMID 30319415, 2018). "Interrogation of public expression databases has shown that increased USP9X mRNA in tumors could significantly anticipate poor outcome for multiple myeloma patients." (PMID 24152793, 2013). "Peterson and colleagues suggested that dual inhibition of USP9X and USP24 by WP1130 provides greater anti-myeloma activity." (PMID 32354135, 2020). "Recently, several reports demonstrated that inhibition of USP9X and/or USP5 by WP1130 leads to apoptotic cell death in malignant peripheral nerve sheath tumors and multiple myeloma." (PMID 30862047, 2019).
Intellectual disability (13 papers, 2015 to 2025). "Loss-of-function mutations in the USP9X gene cause intellectual disability and congenital anomalies, with several craniofacial anomalies observed in the patient." (PMID 40751225, 2025). "Studies indicated that loss-of-function (LOF) mutations in the germline of the USP9X gene cause intellectual disability (ID) and other congenital anomalies." (PMID 40751225, 2025). "Germline loss-of-function mutation of USP9X has been shown to cause intellectual disability as well as other congenital anomalies." (PMID 38755172, 2024). "Mutations in USP9X in humans have been demonstrated to induce intellectual disability by influencing neurogenesis through the ubiquitin signaling pathway." (PMID 38755172, 2024). "Our data corroborate other evidence showing USP9X mutations in males with co-morbid epilepsy conditions (e.g., intellectual disability and ASD)." (PMID 25763846, 2015). "Here, we report a Japanese girl with a novel heterozygous nonsense mutation in USP9X who exhibited intellectual disability with characteristic craniofacial abnormalities, including hypotelorism, brachycephaly, hypodontia, micrognathia, severe dental crowding, and an isolated submucous cleft palate." (PMID 38755172, 2024). "The intellectual disability could therefore be due to the likely pathogenic missense variant in USP9X associated with the impact of the deletion." (PMID 35227307, 2022). "In addition to USP9X, several other members of our identified Prickle-interactome were already implicated in seizures, intellectual disability, and ASD." (PMID 25763846, 2015). "Considering that the present patient exhibited polydactyly and intellectual disability, which are among the core phenotypic features of ciliopathy, the loss of function of USP9X may be mechanistically related to abnormal ciliogenesis, but further studies are needed to confirm this supposition." (PMID 38755172, 2024). "Examples include SUMF1, KDM5B and MXRA5 (Known-ASD genes), PRODH2 and KCTD21 (implicated in schizophrenia), as well as USP9X and SMS (implicated in intellectual disability)." (PMID 28720891, 2017). "USP9X is X-linked; and in males has been associated with both autism spectrum disorder (ASD) and intellectual disability (which are frequently co-morbid with epilepsy)." (PMID 25763846, 2015). "Examples include PRODH2 and KCTD21 (implicated in schizophrenia), USP9X and SMS (implicated in intellectual disability), TRIM9 and KDM5B (known-ASD genes), and others such as AGL and MOGS (candidate genes involved in energy metabolism and immune responses, respectively)." (PMID 28720891, 2017). "A case report of intellectual disability (ID) showed that neuroligin 4 X-linked (NLGN4X, Gene ID: 57502), histone deacetylase 8 (HDAC8, Gene ID: 55869), TATA-box binding protein associated factor 1 (TAF1, Gene ID: 6872), and USP9X genes were associated with XCI escape." (PMID 39891056, 2025). "For example, USP9X and VAMP2 play critical roles in intellectual disability and autism diseases, respectively." (PMID 35794099, 2022). "Mutations in USP9X, encoding an X-linked DUB, cause syndromic and non-syndromic intellectual disability." (PMID 33335288, 2021). "Moreover, patients carrying these USP9X mutations present with clinical features characteristic of MBS without intellectual disability, which is the main clinical feature of USP9X patients." (PMID 39202332, 2024).
colon carcinoma (10 papers, 2012 to 2026). "Consistent with this idea, we found that low USP9X expression was strongly associated with poor survival in colon cancer." (PMID 29346117, 2018). "The results obtained from HCT116 and DLD1 colon cancer cells paralleled those from USP9x siRNA knockdown in HEK293 parental cells, in which pIIIa and RANBP2 expression was significantly increased." (PMID 35709296, 2022). "To test the relationship between USP9X and FBW7 in human cancers, we stained serial sections of human colon cancer TMAs for USP9X and FBW7." (PMID 29346117, 2018). "In terms of a linear model for the expression of USP9X in colon carcinoma, this was found to be significant (P=0.00083)." (PMID 23171055, 2012). "We performed the same analyses in a series of 79 colon tumor samples and observed a moderate correlation between the expression of USP9X and Mcl-1 (r=0.345, P<0.001)." (PMID 23171055, 2012). "For example, USP9X inhibits the formation of colon tumors by stabilizing FBW7 protein." (PMID 39075342, 2024). "Finally, in patients with primary colon cancer gene fusions between USP9X and ERAS have been found, resulting in the constitutive expression of relatively high levels of ERAS." (PMID 34771750, 2021). "In agreement with this idea, we find that a significant percentage of female, but not male, colon cancer patients with USP9X mutations carry a concomitant FBW7 mutation." (PMID 29346117, 2018). "USP32, USP1, USP37, USP12, and USP6 are elevated in macrophages, while USP32, USP9X, USP46, USP12, USP36, and USP24 are upregulated in classical monocytes of colon cancer relative to the control group." (PMID 41356798, 2026).
colorectal cancer (10 papers, 2016 to 2025). A primary or metastatic malignant neoplasm that affects the colon or rectum. "Further, reduced USP9X expression has been associated with poor prognosis in colorectal cancer, consistent with a tumor-suppressive role." (PMID 41413856, 2025). "Reduced USP9X levels in colorectal cancer are associated with reduced FBW97 levels and poor prognosis." (PMID 29652830, 2018). "Among these, USP9X emerged as a novel significantly mutated gene in colorectal cancer." (PMID 41413856, 2025). "The oncogenic driving potential of USP9X was confirmed in several tumor types: loss of function of the gene in chronic myelogenous leukemia, hepatocellular or colorectal carcinoma, bladder cancer and B-cell ALL leads to increased sensitivity to chemotherapy and to apoptosis." (PMID 27602765, 2016). "Collectively, these findings support USP9X as a biologically relevant and potentially functionally important regulator in colorectal cancer pathogenesis, warranting further investigation of its role in tumor progression and as a potential therapeutic target." (PMID 41413856, 2025). "Another study found that USP9X inhibits tumour formation by regulating the stability of the FBW7 protein in colorectal cancer." (PMID 34856948, 2021). "FBW7 levels are frequently decreased in colorectal cancers and the deubiquitinase USP9X acts as a positive regulator of FBW7 stability." (PMID 29652830, 2018). "USP9X promotes FBW7 stability and suppresses colorectal cancer progress." (PMID 34112167, 2021).
hepatocellular carcinoma (9 papers, 2014 to 2024). A malignant tumor that arises from hepatocytes. "Another mechanism is suggested by the observation that the expression of BCL9 can be induced by hypoxia in human hepatocellular carcinoma: BCL9 levels can also be stabilized by the deubiquitinase USP9X in a variety of cancer cell lines." (PMID 34545187, 2021). "USP9X also promotes the progression of hepatocellular carcinoma by targeting β-catenin." (PMID 39075342, 2024).
melanoma (9 papers, 2016 to 2025). A malignant, usually aggressive tumor composed of atypical, neoplastic melanocytes. "We further demonstrated that Ets-1 promotes NRAS gene expression, which may at least partly underlie the high sensitivity of melanoma to Usp9x inhibition and Ets-1 depletion." (PMID 28198367, 2017). "We found that Usp9x KD or inhibition induced major changes in the melanoma ubiquitylome when assessed by ubiquitin-remnant enrichment, suggesting that modification of multiple proteins could underlie the observed effects of Usp9x on melanoma." (PMID 28198367, 2017). "Usp9x KD blocked the induction of SOX2 by vemurafenib or MEKi treatment in melanoma cell lines with mutant BRAF, A375, SK-Mel28 and wild type BRAF, SK-Mel147." (PMID 33613844, 2021). "Human primary melanoma tumor explants (established in NSG mice) show that both Usp9x DUB activity and SOX2 expression are elevated in metastatic tumors when compared to those with inefficient metastatic activity." (PMID 33613844, 2021). "Here we show that ubiquitin-specific peptidase 9, X-linked (Usp9x), a deubiquitinase (DUB) enzyme controls SOX2 levels in melanoma." (PMID 33613844, 2021). "We have previously shown that G9 inhibited Usp9x activity in vitro and in vivo and led to melanoma tumor inhibition and regression." (PMID 33613844, 2021). "In conclusion, our work provides a rationale for the development of a Usp9x inhibitor (small molecule) for overcoming resistance to treatment by MAPK/ERK inhibitors via depletion of SOX2 in melanoma and other tumors including prostate." (PMID 33613844, 2021). "We identified SOX2 as a substrate of Usp9x in melanoma and determined that SOX2 escapes proteasomal destruction by Usp9x-mediated deubiquitination." (PMID 33613844, 2021). "Dose response of a panel of melanoma cell lines to G9, showed that BRAF mutant melanoma cells were sensitive to G9, and the degree of sensitivity correlated with Usp9x and SOX2 expression." (PMID 33613844, 2021). "Considered together, our results indicate that SOX2 is a polyubiquitinated protein with an unexpectedly high turnover rate in melanoma cells which can be controlled by the deubiquitinase Usp9X." (PMID 33613844, 2021). "Accordingly, USP9X depletion in melanoma cell-derived tumours abrogated growth in mouse xenograft models, while its over-expression significantly increased tumour expansion." (PMID 34066106, 2021). "Correlation of expression of SOX2 and Usp9x is evident in cell line models so we next interrogated this in human primary melanoma cells and metastatic tumors." (PMID 33613844, 2021). "Usp9x expression was found to be moderately high in metastatic patients as reported in 19 patient-derived primary melanoma cells." (PMID 33613844, 2021). "Usp9x inhibition provides an avenue for new treatment options for patients with melanoma who either have endogenously high SOX2 or can induce SOX2 upon treatment with kinase inhibitors, especially as a combination with other therapies." (PMID 33613844, 2021). "Usp9x knockdown in melanoma increased SOX2 ubiquitination, leading to its depletion, and enhanced apoptotic effects of BRAF inhibitor and MEK inhibitors." (PMID 33613844, 2021). "We noted that melanoma was unexpectedly dependent on Usp9x for 3D growth and in vivo expansion, with potential Usp9x addiction noted in NRAS mutant melanoma." (PMID 28198367, 2017). "Usp9x and Ets-1 levels are coincidently elevated in melanoma with highest levels detected in metastatic tumours versus normal skin or benign skin lesions." (PMID 28198367, 2017). "Here the authors show that Usp9x regulates the stability of the transcription factor Ets-1 that in turn impacts metastatic melanoma through increased expression of NRAS." (PMID 28198367, 2017). "Overall, Usp9x appears to control ubiquitination of proteins essential in melanoma 3D growth (Ets-1) and attenuation of kinase signalling (Dusp4)." (PMID 28198367, 2017).
melanoma (continued). "Within this hit list, we identified Ets-1 as a Usp9x substrate and key mediator of Usp9x dependence in melanoma." (PMID 28198367, 2017). "To define a mechanism for regulation of NRAS expression by Usp9x in melanoma, we examined the effect of Usp9x (or Ets-1) on NRAS promoter activity." (PMID 28198367, 2017). "Hence, our data suggest that Usp9x depletion leads to robust kinase inhibitor induced apoptosis of melanoma cells which is most likely mediated by decreased SOX2 protein." (PMID 33613844, 2021). "In addition, treatment with Usp9x inhibitor G9 for 3 days also inhibited melanoma growth in matrigel-3D cultures." (PMID 33613844, 2021). "Thus, inducing degradation of SOX2 via Usp9x inhibition is a promising therapeutic approach to overcome this adaptive resistance in melanoma." (PMID 33613844, 2021). "We further demonstrated that Usp9x KD led to SOX2 proteasomal degradation in melanoma." (PMID 33613844, 2021). "Similar effects were noted in both NRAS and BRAF mutant melanoma cells following Ets-1 or Usp9x KD." (PMID 28198367, 2017). "To determine whether Usp9x-targeting agents could have clinical value in melanoma patients, we evaluated G9 activity in an in vivo model of NRAS mutant melanoma." (PMID 28198367, 2017). "Through Usp9x-mediated, site-specific deubiquitination, Ets-1 proteasomal destruction is inhibited, resulting in Ets-1 accumulation and increased melanoma tumorigenicity, which could be blocked by inhibition of Usp9x activity or knockdown of Ets-1." (PMID 28198367, 2017). "Our studies indicate that Usp9x may be a good therapeutic target in melanoma because of its effects on tumour expansion, regulation of Ets-1 stability, NRAS expression and response to kinase inhibitors." (PMID 28198367, 2017). "In addition, ETS1 has been identified to be deubiquitinated by Usp9x in melanoma." (PMID 40369168, 2025). "Therefore, we conducted an unbiased assessment of Usp9x-regulated ubiquitination in NRAS mutant melanoma to define potential targets and pathways that could mediate NRAS regulation." (PMID 28198367, 2017). "Thus, Usp9x-mediated regulation of NRAS expression in melanoma, particulalrly in NRAS mutant cells, may partly underly their dependence on Usp9x for continual expansion and survival." (PMID 28198367, 2017). "However, other Usp9x substrates may also add (for example, Mcl-1) or diminish (for example, Dusp4) anti-tumour activity of Usp9x inhibition and will need to be further examined in melanoma and other tumours." (PMID 28198367, 2017). "Thus, we provide evidence that Usp9x plays an important role in Ets-1 regulation and melanoma tumorigenicity, in part through NRAS transcription which may be of particular importance in tumours driven by NRAS mutation." (PMID 28198367, 2017). "To further assess long-term consequences of Usp9x and SOX2 inhibition, we analyzed the ability of melanoma cells to form colonies in 3-dimensional (3D) growth conditions in matrigel that more closely recapitulates tumor growth in vivo." (PMID 33613844, 2021). "We also examined expression levels of Usp9x and SOX2 in fresh tumor tissue from melanoma patients primary or metastatic sites." (PMID 33613844, 2021). "We showed that similar to Usp9x KD, G9 treatment also decreased SOX2 levels in BRAF-mutant melanoma cells and MG132 treatment reversed the reduction of SOX2 by G9." (PMID 33613844, 2021). "We examined Usp9x and SOX2 expression levels in a panel of BRAF- and NRAS-mutant melanoma cell lines." (PMID 33613844, 2021). "Here we show that Usp9x plays a key role in SOX2 regulation and in melanoma tumorigenicity, particularly in tumors driven by BRAF mutation and dependent on SOX2." (PMID 33613844, 2021). "Upon Usp9x KD, colony growth in 3D culture was blocked in both BRAF (A375) and NRAS (WM1366)-mutant melanoma cells." (PMID 33613844, 2021). "NRAS mutant melanoma cell growth and survival relies on continual NRAS expression, implying that USP9X-mediated stabilisation of ETS-1 drives tumorigenesis." (PMID 34066106, 2021).